ENSG00000260170 (novel protein)
Gene: Protein-coding gene on chromosome 15 (45,587,351 to 45,676,314, forward strand). Ensembl gene ENSG00000260170.
Genetic constraint (gnomAD): Loss-of-function variants: 27 observed, 30.61 expected, observed/expected ratio (o/e) 0.88, 90% interval 0.65 to 1.22. Missense variants: 367 observed, 351.26 expected, observed/expected ratio (o/e) 1.04, 90% interval 0.96 to 1.14. Synonymous variants: 155 observed, 138.87 expected, observed/expected ratio (o/e) 1.12, 90% interval 0.98 to 1.27.